PAK4 (p21 (RAC1) activated kinase 4)
Diseases named in the same sentence as PAK4 in open-access papers (continued):
Sharing a sentence is not in itself a finding about the gene and the disease.
gastric cancer (continued). "It has been revealed that PAK4 phosphorylates SCG10 at Ser50 modulates gastric cancer metastasis." (PMID 32549768, 2020). "LCH-7749944 moderately inhibited PAK4 activity with a half-maximal inhibitory concentration (IC50) of 14.93 μM and effectively suppressed the proliferation, migration, and invasion of human gastric cancer cells through downregulation of several PAK4-dependent pathways." (PMID 29443911, 2018). "PAK4 silenced CDDP gastric cancer cells were then subcutaneously injected into nude mice." (PMID 27845911, 2017). "In summary, our data showed that GL-1196 could suppress the proliferation and invasion of gastric cancer cells via targeting PAK4 and inhibiting PAK4-mediated signaling pathways." (PMID 27077843, 2016). "Moreover, GL-1196 prominently inhibited the invasion of human gastric cancer cells in parallel with blockage of the PAK4/LIMK1/cofilin pathway." (PMID 27077843, 2016). "PAK4 overexpression is reported in various cancers including ovarian, colon and gastric cancers." (PMID 27542207, 2016). "Moreover, PAK4 has recently been found to confer cisplatin resistance in gastric cancer cells or in glioma." (PMID 26411419, 2015). "Potent inhibition of PAK4 by LCH-7749944 suppressed invasion of human gastric cancer cells." (PMID 27919028, 2014). "In addition, a recent study suggested the role of PI3/Akt and ERK pathways in the PAK4-induced cisplatin resistance in gastric cancer cells." (PMID 25238288, 2014). "To explore the effect of PAK4 on CDDP resistance in gastric cancer cells, we first established two CDDP-resistant gastric cancer cell lines-AGS/CDDP and MKN-45/CDDP by continuous exposure to CDDP starting at 0.1 μg/ml and increasing in a stepwise manner to 1 μg/ml." (PMID 27919028, 2014). "Our results demonstrate that PAK4 confers CDDP resistance in gastric cancer cells via the activation of MEK/ERK (MAPK or mitogen-activated protein kinase/extracellular-signal-regulated kinase) and PI3K/Akt (phosphoinositide 3-kinase/protein kinase B or PKB) pathways." (PMID 27919028, 2014). "It was critical to determine whether PAK4 confers CDDP resistance in gastric cancer cells in vivo." (PMID 27919028, 2014). "PAK activity and the PAK-related signaling pathway was downregulated by a small-molecule drug that was designed for gastric cancer cells, and among these were: curcumin for PAK1 and GL-1196, and LC-0882, and LCH-7749944 for PAK4." (PMID 36230657, 2022). "It suppressed the invasion of human gastric cancer SGC7901 cells and alleviated metastasis related SCG10 phosphorylation through downregulation of the PAK4/LIMK1/cofilin and the downstream protein SCG10 signaling pathways." (PMID 36105226, 2022). "PAK4 can weaken the growth inhibition mediated by the TGF-β1/small mother against the decapentaplegic (Smad) pathway, which may cause gastric cancer (GC)." (PMID 35800076, 2022). "In order to detect the effect of the interaction between PAK4 and CORO1C on the migration of gastric cancer cells, transwell assay was performed." (PMID 35593474, 2022). "In this study, we explored the molecular mechanism by which Ser99-phosphorylated PAK4 is released from GEF-H1/Tctex-1 complex on microtubule and is recruited to the leading edge of the gastric cancer cell by binding to CE domain of CORO1C." (PMID 35593474, 2022). "The PAK4-mediated activation of MEK/ERK and PI3K/AKT was validated in cisplatin-resistant gastric cancer cells." (PMID 36230657, 2022). "PAK4S99A-overexpressing gastric cancer cell showed weaker migration and invasion capabilities than cells overexpressing PAK4S99D or wild-type PAK4, as revealed by transwell and wound healing assays." (PMID 35593474, 2022). "Our results confirmed that phosphorylation at serine 99 distributed PAK4 to the cell membrane, and interestingly, this phosphorylation is also required for CORO1C-promoted migration of gastric cancer cells." (PMID 35593474, 2022).
gastric cancer (continued). "PAK4 regulates cell migration mainly dependent on the downstream pathways of LIMK1/cofilin in prostate cancer and gastric cancer." (PMID 28440035, 2017). "Therefore PAK4 may be a potential target for adjuvant chemotherapy in gastric cancer." (PMID 27919028, 2014). "Therefore, PAK4 may be a potential target for overcoming CDDP resistance in gastric cancer therapy." (PMID 27919028, 2014). "LCH-7749944 was found to suppress gastric cancer cell proliferation and invasion via inhibition of the PAK4/c-Src/EGFR/cyclin D1, PAK4/LIMK1/cofilin and PAK4/MEK-1/ERK1/2/MMP2 pathways." (PMID 25093037, 2014). "This study was designed to explore the potential relationship between PAK4 and CDDP resistance in gastric cancer cells." (PMID 27919028, 2014). "Therefore, PAK4 may be a potential target for overcoming CDDP resistance in gastric cancer." (PMID 27919028, 2014). "Based on its dual effect on the conserved residues Leu 398 (PAK4) and Leu 347 (PAK1) within the hinge region, subsequent studies have showcased the inhibitory potential of LCH-7749944 against the invasive metastasis of gastric cancer cells." (PMID 40332759, 2025). "Once phosphorylated, PAK4 is released from microtubule, and then is recruited by CORO1C to the leading edge and regulates the CORO1C/RCC2 (regulator of chromosome condensation 2) complex, leading to the migration of gastric cancer cells." (PMID 35593474, 2022). "Once phosphorylated, PAK4 is released from microtubules, and then is recruited by CORO1C to the leading edge and regulates the CORO1C/RCC2 complex, leading to the migration of gastric cancer cells." (PMID 35593474, 2022). "GST pull-down assay showed that though RCC2 interacted with CORO1C∆CE, the membrane co-localization of RCC2 with CORO1C∆CE disappeared, while further PAK4 knockdown also ceased both the interaction of RCC2 with CORO1C and the leading edge co-localization of RCC2 in gastric cancer cells." (PMID 35593474, 2022). "We further determined whether the interaction between PAK4 and RCC2 is necessary for the migration of gastric cancer cells by transwell assay using cells with knockdown ofPAK4 orRCC2." (PMID 35593474, 2022). "Conversely, treatment with the PI3K inhibitor LY294002 in the wild type CDDP gastric cancer cells, led to a reduction of phosphorylated PAK4 compared with control cells without affecting total PAK4 expression." (PMID 27845911, 2017). "Expression of wild-type and constitutively active PAK4 induced a significant increase in cellular proliferation in ovarian cancer cells, and it was reported to repress TGF-β-mediated growth inhibition in gastric cancer cells." (PMID 27077843, 2016). "Therefore the data together indicate that PAK4 and PI3K/Akt pathway reciprocally activate each other in CDDP-resistant gastric cancer cells." (PMID 27919028, 2014). "Notwithstanding these limitations, our study does indicate that PAK4 confers CDDP resistance via activation of MEK/ERK and PI3K/Akt pathways and there exists a reciprocal activation between PAK4 and PI3K/AKT pathways in gastric cancer cells in vitro." (PMID 27919028, 2014). "In gastric cancer, PAK4 overexpression was found in four (8.1%) of 49 metastatic cancer specimens and none of the four patients with PAK4(+) responded to capecitabine/cisplatin chemotherapy." (PMID 27919028, 2014). "There exists mutual activation between the PAK4 and PI3K/Akt pathways in gastric carcinoma cells." (PMID 25003395, 2014). "In addition, as the kinase activity of PAK4 is inhibited by two inhibitors, the downstream LIMK1/cofilin signaling pathway of PAK4 is also suppressed, ultimately inhibiting the migration and invasion of gastric cancer cells." (PMID 40332759, 2025). "However, PAK4 mainly focuses on the regulation of the migration, metastasis and invasion (via LIMK1/Cofilin/microfilament, SCG10/microtubule, DGCR6L, Coro1C) of gastric cancer cells." (PMID 36230657, 2022).
gastric cancer (continued). "Since we have detected that GL-1196 has an inhibitory effect on proliferation and invasion in gastric cancer cells, it is an attractive option for us to explore if GL-1196 could target PAK4 or not." (PMID 27077843, 2016). "Thus, it is reasonable that GL-1196 suppressed the PAK4/c-Src/EGFR/cyclinD1 pathway and CDK4/6 expression, which, in turn, inhibited the transition of cells from G1 to S phase, and finally resulted in the anti-proliferative effect on gastric cancer cells." (PMID 27077843, 2016). "The reciprocal activation between PAK4 and PI3K/AKT pathways may represent a positive regulatory circuit that mutually reinforces the PAK4 and Akt activities to further augment the CDDP resistance in gastric cancer." (PMID 27919028, 2014).
prostate carcinoma (25 papers, 2013 to 2025). A carcinoma that arises from epithelial cells of the prostate gland. "Genes previously implicated in prostate cancer (PAK4, TNK2) and genital dysplasia (ROR2) also demonstrated mutations." (PMID 28423512, 2017). "Consistently, the PAK4-mediated induction of the EMT has been seen in prostate cancer cells and renal tubular epithelial cells." (PMID 39273017, 2024). "A similar effect has been observed in prostate cancer, where targeting PAK4 increases the infiltration of CD8 T cells and B cells into the tumour, reversing PD-1 blockade resistance." (PMID 38067120, 2023). "In mice with syngeneic prostate cancer, knockdown or pharmacological inhibition of p21-activated kinase-4 (PAK4) sensitized to PD1 Ab." (PMID 37686465, 2023). "PAK4 also regulates the focal adhesion via binding and phosphorylating paxillin of prostate cancer cells." (PMID 36230657, 2022). "In this article, we review the PAK4 signaling pathways involved in prostate cancer, Parkinson’s disease, and melanogenesis, focusing in particular on the PAK4-CREB axis." (PMID 30755582, 2019). "In the current review, we have highlighted the role of PAK4 signaling in many biological events, including prostate cancer progression, neuroprotection in Parkinson’s disease, and the promotion of melanogenesis." (PMID 30755582, 2019). "PAK4, for example, has been shown to promote CREB’s gene-activating function in prostate cancer, and PAK4 overexpression is a feature of numerous other tumor types." (PMID 30755582, 2019). "Recent studies have shown that TACSTD2 has a critical role in the metastasis of prostate cancers by modulating β1 integrin function, and activation of PAK4 induced by TACSTD2 was observed in the experiment." (PMID 25202389, 2014). "Similarly, it is reported in different cancers with agents that activate cAMP that they can activate PAK4, such as thyroid-stimulating hormones in papillary thyroid cancer, C-X-C motif chemokine 12 in prostate cancer and alpha-MSH in B16 melanoma cells." (PMID 40001881, 2025). "In prostate cancer, inhibition of PAK4 increased the width of blood vessels in the tumour context." (PMID 38067120, 2023). "PAK4 promotes prostate cancer cell migration via its kinase substrates such as LIMK1." (PMID 36230657, 2022). "It has been shown that PAK4 phosphorylating Slug to promote EMT in prostate cancer." (PMID 32549768, 2020). "In addition, in migratory human prostate cancer cells, p21-activated kinase 4 (PAK4) was localized at focal adhesions, and was immunoprecipitated with paxillin and phosphorylated paxillin on Ser-27235." (PMID 31101859, 2019). "Moreover, forskolin can activate PAK4 in papillary thyroid cells and in prostate cancer cells." (PMID 40001881, 2025). "Recent studies have demonstrated that the inhibition of PAK4 increased CD8+ T cell infiltration in immune-resistant melanoma and prostate cancer and synergized with immune checkpoint inhibitors in suppressing cancer growth." (PMID 39941877, 2025). "Consistently, a higher expression of PAK4 increased the proliferation and migration activity of MG63 osteosarcoma cells, ovarian cancer cells, and prostate cancer cells." (PMID 39273017, 2024). "Recently, PAK4 was shown to suppress T cell response in melanoma, prostate cancer, and glioblastoma, which is consistent with an observed upregulation of intra-tumoral CD8 + T cells in PDA mouse model by PAK4 inhibitor PF-3758309." (PMID 38797819, 2024). "In a recent study, we discovered that PAK4 regulates the transcriptional activity of CREB and thereby promotes prostate cancer progression through such mechanisms as the emergence of drug resistance and neuroendocrine differentiation." (PMID 30755582, 2019). "HGF is a potent agonist of tumor progression and invasiveness, and PAK4 is required for HGF-induced progression and invasion of human prostate cancer cells." (PMID 30755582, 2019).
prostate carcinoma (continued). "PAK4 binds and directly phosphorylates Slug at Ser158 and Ser254 which resulted in the stabilization of Slug, and further induces EMT, and the invasion and metastasis of prostate cancer cells." (PMID 36230657, 2022). "Thus, the interaction between PAK4 and LIMK1 could be an essential factor in prostate cancer invasiveness." (PMID 36899941, 2023). "Notably, overexpression of PAK4 was detected in biopsies of tumor patients who lack immune cell infiltration and negative correlation between PAK4 expression and T cell infiltration has been evidenced in various tumors, such as pancreatic and prostate cancers featuring poor PD-1 blockade response." (PMID 36105226, 2022).
ovarian cancer (24 papers, 2014 to 2025). A primary or metastatic malignant neoplasm involving the ovary. "High PAK4 activity associated with poor prognosis in ovarian cancer patients." (PMID 28407679, 2017). "Therefore, in this study, we investigated whether Pak4 expression was associated with clinicopathological parameters of ovarian cancer." (PMID 38807162, 2024). "More importantly, we found that Pak4 expression level was highly affected by different histological types of ovarian cancer, highlighting importance of ovarian cancer heterogeneity." (PMID 38807162, 2024). "Pak4 level significantly correlated with histological parameters and prognosis of ovarian cancer patients." (PMID 38807162, 2024). "Single cell sequencing database proved that Pak4 was highly expressed in malignant ovarian cancer cells." (PMID 38807162, 2024). "In this study, we used immunohistochemistry to investigate into Pak4 expression in different histological types of ovarian cancer." (PMID 38807162, 2024). "Overall, our preclinical data suggest that inhibiting NAMPT and PAK4 by KPT-9274 is an effective approach to overcome platinum resistance in ovarian cancers." (PMID 38424218, 2024). "Our results demonstrated the expression level, gene interaction networks and immune infiltration levels of Pak4 in ovarian cancer." (PMID 38807162, 2024). "Pak4 expression level in ovarian cancer was higher than in normal ovary tissue using GEPIA (P > 0.05; num (T) = 426; num (N) = 88)." (PMID 38807162, 2024). "To further characterize the impact of NAMPT and PAK4 in ovarian cancer, we evaluated the ovarian cancer RNA sequencing data from TCGA." (PMID 38424218, 2024). "The GSCA website further consolidated the fact that low Pak4 expression level was positively connected with better OS in ovarian cancer (higher expression, n = 152; lower expression, n = 153) (logrank P value = 0.05)." (PMID 38807162, 2024). "The single cell sequencing database of TISCH2 demonstrated high Pak4 expression in malignant ovarian cancer cells based on several datasets." (PMID 38807162, 2024). "In conclusion, KPT-9274 demonstrated a promising activity against NAMPT or PAK4-driven cancer growth, suggesting it is a potential novel treatment for platinum-resistant ovarian cancer." (PMID 38424218, 2024). "String showed partially consistent gene networks, suggesting further investigation of Pak4 mechanism in ovarian cancer." (PMID 38807162, 2024). "Pak4 level correlated closely with immune infiltration and T cell exhaustion in ovarian cancer microenvironment." (PMID 38807162, 2024). "The rate of Pak4 staining was represented as -, +, ++, +++, and they were respectively found in 6.7% (11/163), 15.3% (25/163), 37.4% (61/163), 40.5% (66/163) of ovarian cancer patients." (PMID 38807162, 2024). "TIMER, TISCH2, GEPIA, ualcan, KM plotter, GSCA and GeneMANIA were used to identify the prognostic roles and gene regulation networks of Pak4 in ovarian cancer." (PMID 38807162, 2024). "The 203154_s_at probe showed that low Pak4 expression was correlated with better OS in ovarian cancer (HR = 1.22 (1.07–1.4), logrank P = 0.0038) as well as the PFS (HR = 1.22 (1.07–1.39), logrank P = 0.003)." (PMID 38807162, 2024). "Accumulated evidence supports a critical role for abnormal PAK4 expression in oncogenesis, and amplification or activation of PAK4 has been detected in numerous cancers, including pancreatic, breast, and ovarian cancers." (PMID 34912075, 2022). "Studies have pointed out that PAK4 modulates ovarian cancer tumor progression via c-Src/ERK1/2 and EGFR/MMP2 signal pathway." (PMID 32549768, 2020). "Pak1 and Pak4 promote ovarian cancer cell migration and invasion through the p38/VEGF pathway and the c-Src/MEK-1/MMP2 pathway, respectively." (PMID 26218748, 2015). "We have recently identified Pak1 and Pak4 as prognostic markers and potential therapeutic targets for ovarian cancer." (PMID 26218748, 2015).